UBE2L3 (ubiquitin conjugating enzyme E2 L3)
Diseases named in the same sentence as UBE2L3 in open-access papers (continued):
Sharing a sentence is not in itself a finding about the gene and the disease.
Hypoglycemia (3 papers, 2021 to 2022). A decreased concentration of glucose in the blood. "In follow-up after hypoglycemia, HSPs normalized to baseline by 24 h, except UBE2L3 (p < 0.05), which was decreased in controls versus baseline." (PMID 34831332, 2021). "In accord with the findings in severe hypoglycemia, there were significant increases in UBE2N, STIP1, and UBE2L3 seen in hypoglycemia only in the T2D cohort that returned to baseline by 24 h." (PMID 34831332, 2021). "In the follow-up period after hypoglycemia, HSPA8 remained lower in T2D (p < 0.05), UBE2L3 (p < 0.05) was decreased in controls compared to baseline, and the other HSPs normalized to baseline by 24 h." (PMID 34831332, 2021). "In the post-hypoglycemia follow-up period, most proteins normalized to baseline by 24-h; however, STIP1 (p = 0.003), UBE2N (p = 0.004) and UBE2L3 (p < 0.04) were decreased in controls at 24-h." (PMID 34426634, 2021). "At hypoglycemia, UBE2N, STIP1, and UBE2L3 increased (all p < 0.05), whilst TLR4:MD-2 and HSPA8 decreased (p < 0.05) in T2D versus baseline." (PMID 34831332, 2021). "At hypoglycemia, UBE2N, STIP1, and UBE2L3 increased in T2D compared to baseline (p < 0.05, p < 0.05, and p < 0.05, respectively), a change not seen in controls." (PMID 34831332, 2021). "In the time course following hypoglycemia, UBE2N, UBE2L3 and STIP1 were significantly and persistently higher in T2D compared to normal controls for up to 24-h, suggesting that in T2D the heat shock and related proteins are preconditioned for an enhanced response." (PMID 34426634, 2021). "Notably UBE2N, UBE2L3, and STIP1 all significantly go down in controls but not at all in T2D in response to hypoglycemia, whilst the protein that is linked within the system, UBE2G2, was unaffected by hypoglycemia, though significantly lower than levels seen in T2D at all time points." (PMID 34426634, 2021). "Why the levels of UBE2N, UBE2L3 and STIP1 should fall in the control subjects in response to hypoglycemia, whilst UBE2G2 showed no apparent change in level, is unclear, and whether the loss of regulation of these specific and tightly controlled proteins would lead to a detrimental effect is unknown." (PMID 34426634, 2021).
non-small cell lung carcinoma (3 papers, 2020 to 2024). A group of at least three distinct histological types of lung cancer, including non-small cell squamous cell carcinoma, adenocarcinoma, and large cell carcinoma. "In contrast, UBE2L3, associated with the SCF ubiquitin ligase complex, promotes non-small cell lung cancer by ubiquitinating and degrading p27kip1 and glycogen synthase kinase 3β (GSK-3β)." (PMID 38226814, 2024). "A study reported that UBE2L3 promotes the ubiquitination and degradation of p27kip1 in non-small-cell lung cancer (NSCLC), and further study suggested that high expression of UBE2L3 led to the down-regulation of p27KIP1 protein levels, which are relevant to a poor prognosis for NSCLC." (PMID 35265070, 2022).
osteosarcoma (3 papers, 2020 to 2023). A usually aggressive malignant bone-forming mesenchymal neoplasm, predominantly affecting adolescents and young adults. "The results showed that the mRNA expression level of four ubiquitin-related genes (CORO6, UBE2L3, FBXL5, DNAI1) was significantly increased in osteosarcoma tissues as compared with adjacent normal tissues." (PMID 36060009, 2022). "The expression of ubiquitin-related genes (CORO6, UBE2L3, FBXL5, DNAI1, and DCAF8) showed an obvious significance in normal and osteosarcoma tissues." (PMID 36060009, 2022). "Likewise, DCAF8 lncRNA-associated mRNA, DCAF8, is a ubiquitin-related gene that decreased in osteosarcoma tissues, and together with other ubiquitin-related genes (CORO6, UBE2L3, FBXL5, DNAI1) seem to play a significant role in the clinical outcome of osteosarcoma." (PMID 36831395, 2023).
prostate carcinoma (3 papers, 2020 to 2022). A carcinoma that arises from epithelial cells of the prostate gland. "Our study suggested that lncRNA LINC01116 acted as an oncogene in prostate cancer and accelerated prostate cancer cell growth through regulating miR-744-5p/UBE2L3 axis." (PMID 33726770, 2021). "So we took UBE2L3 as the experimental mRNA, from qRT-PCR, and UBE2L3 was discovered to be abnormally upregulated in prostate cancer cells." (PMID 33726770, 2021). "Our study also manifested UBE2L3 presented a high expression in prostate cancer cells, and overexpression of UBE2L3 also led to enhanced proliferative, migratory and invasive capabilities of prostate cancer cells." (PMID 33726770, 2021). "For the sake of investigation into the regulatory mechanism of LINC01116 in prostate cancer cells, with miR-744-5p and UBE2L3 involved, we conducted rescue assays." (PMID 33726770, 2021). "In rescue assays, we discovered that inhibited miR-744-5p or overexpressed UBE2L3 could offset the suppressive influence of silencing LINC01116 on prostate cancer cells." (PMID 33726770, 2021). "The present study showed that LINC01116 displayed a high level in prostate cancer cells, and could regulate miR-744-5p/UBE2L3 axis to promote cell growth of prostate cancer." (PMID 33726770, 2021). "Thus, it was confirmed that UBE2L3 accelerated prostate cancer cell proliferative, migratory and invasive capabilities." (PMID 33726770, 2021). "Another study identified the oncogenic UBE2L3-KRAS fusion in DU145 prostate cancer cells using an integrative genomics approach, and further investigation demonstrated that the fusion of UBE2L3 with KRAS may lead to the progression of metastases in rare subsets of prostate cancer." (PMID 35265070, 2022). "Therefore, LINC01116 could promote cell growth of prostate cancer by regulating miR-744-5p/UBE2L3 axis." (PMID 33726770, 2021).
Alzheimer disease (2 papers, 2019 to 2025). A progressive, neurodegenerative disease characterized by loss of function and death of nerve cells in several areas of the brain leading to loss of cognitive function such as memory and language. "The UBE2L3 protein is an E2 conjugation enzyme that is involved in the ubiquitination of many proteins and has been reported to be altered in Alzheimer’s disease." (PMID 40869913, 2025). "We combined this hub gene analysis with GWAS association gene scores, and observed that PSMB5, UBE2L3, and PSMD3 are important in many age-related diseases or phenotypes, such as Alzheimer’s disease, HDL cholesterol, LDL cholesterol, triglycerides, and insulin resistance." (PMID 31269015, 2019).
gastric cancer (2 papers, 2018 to 2024). A primary or metastatic malignant neoplasm involving the stomach. "The objective of this study is to examine the expression and importance of UBE2L3 in human gastric cancer tissues." (PMID 38656363, 2024). "The identification of UBE2L3 and the prospect of further comprehensive investigation suggest the potential for significant advancements in targeted therapy for gastric cancer." (PMID 38656363, 2024). "The collective data presented above suggest that the suppression of UBE2L3 hinders the growth of gastric cancer in an in vivo setting." (PMID 38656363, 2024). "The findings of our study demonstrate the significant involvement of UBE2L3 in the pathogenesis and advancement of gastric cancer, suggesting its potential as a therapeutic target." (PMID 38656363, 2024). "Nevertheless, further research is required to elucidate the mechanism through which UBE2L3 facilitates tumor initiation and progression in gastric cancer." (PMID 38656363, 2024). "Subsequently, the biological function of UBE2L3 in gastric cancer was validated through a series of laboratory methods." (PMID 38656363, 2024). "Nevertheless, the specific function of UBE2L3 in gastric cancer remains unclear." (PMID 38656363, 2024). "The study revealed that the expression levels of UBE2L3 mRNA were significantly elevated in the majority of gastric cancer tissues compared to adjacent non-tumor gastric tissues, as determined through analysis of publicly available databases." (PMID 38656363, 2024).
liver cancer (2 papers, 2022 to 2024). An epithelial or non-epithelial malignant neoplasm that arises from the liver. "For example, UBE2L3 was generally upregulated in clinical liver cancer samples compared to non-tumour samples, may be an important pro-tumorigenic factor in liver carcinogenesis." (PMID 38795139, 2024).
lung carcinoma (2 papers, 2017 to 2024). "We then investigated the functional role of UBE2L3 in promoting lung cancer progression." (PMID 29137415, 2017). "Thus, CUL1 and UBE2L3 might have double-edged functions for tumor promotion in lung cancer while suppressing HPV+ cancers through E7 degradation." (PMID 38226814, 2024). "However, there still lack a comprehensive analysis between UBE2L3 and lung cancer." (PMID 29137415, 2017).
Obesity (2 papers, 2014 to 2022). Accumulation of substantial excess body fat. "To test transcriptional effects of miR-125a down-regulation in human obesity, we quantified the expression of its target genes Tef, Masp1, Rtn2, Ube2l3 and Adam9 in subcutaneous adipose tissue samples of obese patients." (PMID 24675842, 2014). "In ConvR HFD mice liver, 17 genes DNA methylation changes including Ube2l3, Etv5, Lrp1, and Nudt3 were determined related to obesity and 11 genes DNA methylation changes including Exoc312, Mst1r, Prkch, and Arhgap26 were determined related to Type 2 diabetes (T2D) in the previous study." (PMID 35458198, 2022). "More specifically Masp1, Tef, Rtn2 and Ube2l3 showed contrasting expression patterns before and after gastric bypass but the effects were statistically significant for Tef only, which highlights a possible specific role of Tef in obesity and IR of obese patients." (PMID 24675842, 2014).
schizophrenia (2 papers, 2014 to 2021). A major psychotic disorder characterized by abnormalities in the perception or expression of reality. "UBE2L3 has been found to be associated with schizophrenia (SZ) in several studies, and one study in particular showed that this gene was found to be significantly related to phenotypic pairs of autoimmune and psychiatric conditions across multiple loci." (PMID 34630024, 2021). "BARD1 signaling pathway contains three under-expressed genes, BARD1, PCNA and UBE2L3, in which UBE2L3 polymorphism is associated with schizophrenia, and polymorphism study reveals that BARD1 is risk allele for schizophrenia." (PMID 25522158, 2014).
AIDS (1 paper, 2018). A syndrome resulting from the acquired deficiency of cellular immunity caused by the human immunodeficiency virus (HIV). "The miRSNP rs7444, which is in the 3′ UTR of the UBE2L3 gene, was associated with three AIDs (SLE, CD, and IBD)." (PMID 29755505, 2018).
Arthritis (1 paper, 2023). Inflammation of a joint. "In humans, polymorphisms in UBE2L3 are associated with inflammatory conditions, including arthritis and inflammatory bowel disease, demonstrating a link between UBE2L3 and deregulated inflammation through as yet unknown mechanisms." (PMID 37474493, 2023).
autism spectrum disorder (1 paper, 2024). A spectrum of developmental disorders that includes autism, and Asperger syndrome. "Another example is Ube2l3, which is the E2 of the ligase enzyme ARIH2 very recently identified mutated in a patient with autism spectrum disorder and intellectual disability." (PMID 39596581, 2024).
autoimmune thyroid disease (1 paper, 2016). Inflammatory disease of the thyroid gland due to autoimmune responses leading to lymphocytic infiltration of the gland. "The aim of this study was to investigate the association between UBE2L3 gene and autoimmune thyroid diseases (AITDs) and their clinical phenotypes." (PMID 27094594, 2016).
bipolar disorder (1 paper, 2023). A disorder of the brain that causes unusual shifts in mood, energy, activity levels and the ability to carry out day-to-day tasks. "However, we can identify five top genes at 22q11.2 associated with BMI (YDJC, CCDC116, PPIL2, THAP7, UBE2L3), primarily located outside the canonical CNV region (LCR D-E), three with bipolar disorder (TMEM191B, TUBA8, PPIL2), six with ASD (CLTCL1, AC004471." (PMID 37267418, 2023).
diabetes (1 paper, 2022).
esophageal squamous cell carcinoma (1 paper, 2024). Esophageal squamous cell carcinoma (ESCC) is a type of esophageal carcinoma (EC) that can affect any part of the esophagus, but is usually located in the upper or middle third. "A recent study showed that membrane-associated ring-CH-type finger 8 (MARCHF8) knockdown in esophageal squamous cell carcinoma cells increases the levels of CUL1 and UBE2L3 proteins." (PMID 38226814, 2024). "By analyzing proteomics data from a previous study in esophageal squamous cell carcinoma, we found that the CUL1 and UBE2L3 proteins are among the cellular proteins increased by the MARCHF8 knockdown." (PMID 38226814, 2024).
lupus nephritis (1 paper, 2015). Glomerulonephritis in the context of systemic lupus erythematosus. "Case-case subphenotype analysis available on a subset of 1,751 SLE case subjects demonstrated that rs140490 was associated with increased risk of lupus nephritis (p = 0.0036, OR 1.27, 95% CI: 1.08–1.49), suggesting that UBE2L3 is associated with increased disease severity." (PMID 25640675, 2015).
psychosis (1 paper, 2021). "Dysregulation of UBE2L3 gene expression from the whole blood of the first episode of psychosis patients compared with healthy control populations was reported recently." (PMID 34630024, 2021).
squamous cell carcinoma (1 paper, 2024). A carcinoma arising from squamous epithelial cells. "On the other hand, UBE2L3 promotes squamous cell carcinoma progression." (PMID 38795139, 2024).
tumor (14 papers, 2017 to 2026). "Autophagy and the tumor microenvironment are closely associated, and we observed that UBE2L3 knockdown in TNBC tumors significantly increased CD8+ T lymphocyte infiltration and enhanced tumor sensitivity to anti-PD-1 therapy." (PMID 41943836, 2026). "Loss of UBE2L3 restricted tumor cell growth by modulating autophagy in TNBC cells." (PMID 41943836, 2026). "These core genes—TRAF4, UBE2L3, FBXO45, UBE2L6, FBXL14, SKP2, CHAF1B, and WDR77—have been implicated in tumor progression in previous studies." (PMID 40990020, 2025). "To investigate if the degradation of HPV16 E7 protein by CUL1 and UBE2L3 inhibits tumor growth, we utilized a C57BL/6J (B6) mouse oral epithelial (MOE) cell line expressing HPV16 E6/E7 and Hras (mEERL) which forms tumors in immunocompetent syngeneic B6 mice." (PMID 38226814, 2024). "Another investigation demonstrated that UBE2L3 facilitated the cellular malignant characteristics of oral squamous cell carcinoma, such as proliferation, invasion, migration, and in vivo tumor growth." (PMID 38656363, 2024). "The results demonstrate that the tumor volume of the sh-NC group was greater than that of the sh-UBE2L3-3 group." (PMID 38656363, 2024). "In contrast, the mice injected with mEERL/Cul1 or mEERL/Ube2l3 cells displayed delayed tumor formation and death by tumor burden." (PMID 38226814, 2024). "The GEPIA public database was utilized for the collection of UBE2L3 mRNA expression data in various tumor tissues, with the aim of further investigating the UBE2L3 mRNA expression in GC tissues." (PMID 38656363, 2024). "The involvement of UBE2L3 in the proliferation, invasion, and apoptosis of GC cells was confirmed through in vitro experiments, and its capacity to facilitate tumor growth was also validated in in vivo studies." (PMID 38656363, 2024). "Studies have found an abnormal expression of UBE2L3 in the cell lines and tumor tissues from many patients with a tumor indicating that UBE2L3 is involved in a number of cancer-related signaling pathways." (PMID 35265070, 2022). "The Ub-conjugating enzyme, UBE2L3, was found to be overexpressed in NSCLC tissues compared with non-tumor tissues, and its high expression was associated with an advanced tumor stage and adverse outcomes." (PMID 34199813, 2021). "Ectopic expression of UBE2L3 promoted NSCLC cell growth in vitro in a cell cycle-dependent manner and NSCLC tumor growth in vivo, while knockdown of UBE2L3 significantly suppressed both in vitro and in vivo NSCLC growth." (PMID 34199813, 2021). "In hepatocellular carcinoma samples, the upregulation of UBE2L3 is also suspected to be the reason for tumor progression." (PMID 34769401, 2021). "In the current work, we found the mRNA and protein levels of UBE2L3 were up-regulated in NSCLC tissues in comparison with non-tumor tissues." (PMID 29137415, 2017). "The results of subcutaneous tumor xenograft studies revealed that knockdown of UBE2L3 attenuated the in vivo tumor growth." (PMID 29137415, 2017). "Results revealed that UBE2L3 expression in NSCLC tissues was higher than that of non-tumor tissues, with a significant difference at the mRNA and protein levels (p<0.01)." (PMID 29137415, 2017). "To determine whether Cul1 and Ube2l3 overexpression suppresses HPV+ HNC tumor growth, we generated mEERL cells overexpressing Cul1 (mEERL/Cul1) or Ube2l3 (mEERL/Ube2l3) using lentiviruses and blasticidin selection." (PMID 38226814, 2024). "In vivo experiments have validated the role of UBE2L3 in promoting tumor growth." (PMID 38656363, 2024). "In vivo experiments, UBE2L3 was found to promote tumor progression." (PMID 38656363, 2024). "Finally, the findings from the hematoxylin and eosin (H&E) staining and immunohistochemistry (IHC) analysis, conducted on tumor tissues, revealed that the levels of UBE2L3 and Ki67 expression were higher in the sh-NC group compared to the sh-UBE2L3-3 group." (PMID 38656363, 2024).